MTOR (mechanistic target of rapamycin kinase)
Diseases named in the same sentence as MTOR in open-access papers (continued):
Sharing a sentence is not in itself a finding about the gene and the disease.
Stroke (92 papers, 2013 to 2026). Sudden impairment of blood flow to a part of the brain due to occlusion or rupture of an artery to the brain. "Collectively, these results indicate that the AKT/mTOR signaling pathway is implicated in triolein’s inhibition of post-stroke inflammation and autophagy." (PMID 39639187, 2024). "GRB2 has been implicated in neuronal autophagy in stroke neuropathology via the suppression of the Akt/mTOR pathway." (PMID 35250546, 2022). "NPRL3 is a known regulator of mTOR activity that promotes neuronal survival in stroke patients and is associated with focal epilepsy." (PMID 33202874, 2020). "Taken together, we provide solid evidence that the protective effect of CD4 T cell deficits in stroke is linked with the inhibited pro-inflammatory and oxidative responses, and with the enhanced activities of the Akt/mTOR pathways." (PMID 32832192, 2018). "Concentrating on the pivotal PI3K/Akt/mTOR signaling pathway and associated factors, exosomes could combat AD, stroke, SCI, traumatic brain injury (TBI), ALS, optic nerve crush (ONC) injury, and other central nervous systems (CNS) injuries." (PMID 36986865, 2023). "Importantly, increased mTOR activity accelerates brain recovery after stroke, and focal epilepsy is associated with the manifestation of ischemic cerebrovascular disease." (PMID 33202874, 2020). "However, given the unique importance of mTOR signaling for skeletal muscle hypertrophy, it is plausible to suggest that stroke-induced downregulation of IGF1 and PI3K-Akt associated genes may reduce protein synthesis and contribute to skeletal muscle atrophy." (PMID 32629989, 2020). "Mammalian target of rapamycin (mTOR) has been shown to play an important role in cell death after stroke." (PMID 39331260, 2025). "Mammalian target of rapamycin (mTOR) inhibition has been shown to reduce motility/contractility of various cancer cell lines and reduce neuronal cell death in stroke." (PMID 39331260, 2025). "The majority of studies on AMPK/mTOR mechanisms following hypoxic-ischemic injury have utilized adult models of stroke, variations in the neonatal Vannucci model of HI, or in vitro models of HI 40-45." (PMID 39744433, 2025). "It is a central part of a protective signaling network called the PI3K/Akt/mTOR pathway, which is particularly important after a stroke." (PMID 41373489, 2025). "Increase functional recovery after stroke via PTEN-mediated PI3K/Akt/mTOR; regulate axon remodeling." (PMID 40565557, 2025). "Stroke research has identified that mammalian target of rapamycin (mTOR) activity is often elevated during a stroke event, and that inhibiting this activity can promote beneficial autophagy, thereby enhancing neuronal survival by removing damaged organelles." (PMID 39026255, 2024). "Our animal experiments revealed that triolein inhibited autophagy and the inflammatory response following stroke by activating the AKT/mTOR signaling pathway." (PMID 39639187, 2024). "This suggests that inhibiting the AKT/mTOR signaling pathway partially counteracted triolein’s ability to inhibit post-stroke inflammation." (PMID 39639187, 2024). "Strategies aimed at fine-tuning mTOR activity, restoring autophagic flux, and mitigating neuroinflammatory responses offer avenues for enhancing stroke outcomes while minimizing adverse effects." (PMID 38666949, 2024). "Activation of the Akt/mTOR pathway helps promote neovascularization which can lead to a reduction in infarct size after stroke." (PMID 38106632, 2023). "This study provides new mechanistic insights into how epalrestat exerts a neuroprotective effect and attenuates the pathogenesis of stroke, implicating the AR/AKT/mTOR pathway as a potential therapeutic target for stroke patients." (PMID 36940077, 2023).
Stroke (continued). "In other studies, catalpol has been shown to activate mTOR and its downstream S6 protein, thereby inducing cellular activity and ultimately activating axonal regeneration after stroke." (PMID 36440366, 2022). "Numerous studies have reported that autophagy is regulated via an mTOR-dependent pathway after stroke." (PMID 35795405, 2022). "A previous study showed that catalpol switched the intrinsic neuronal activity to promote axonal growth via the PI3K/AKT/mTOR signaling pathway after a stroke." (PMID 35305084, 2022). "PTEN or Phosphatase and tensin homolog deleted on chromosome 10 inhibitor drugs administration after stroke is found to confer neuroprotection via improvement of axonal growth and activation of the Akt/mTOR activation." (PMID 35250546, 2022). "Compared to the sham+SC group, the other two groups showed more autophagy and suppressed mTOR expression after stroke." (PMID 35795405, 2022). "In our previous studies, we demonstrated that the activation of mTOR alleviated stroke-related neuronal injury." (PMID 34900085, 2021). "We will highlight lessons learned about optimal dosing of rapamycin in experimental stroke in an attempt to inform dosing of newer generation mTOR inhibitors such as Rapalink-1, to achieve brain cytoprotection." (PMID 34630168, 2021). "Another protein shown to inhibitor mTOR activity, Sestrin2, a stress-inducible protein, when delivered intranasally, improves stroke outcome (decreased infarct volume, improved cognition) following hypoxia-ischemia." (PMID 33233734, 2020). "The results of our sequencing analysis revealed stroke-induced differential expression of several PI3k-Akt-mTOR genes." (PMID 32629989, 2020). "We and others have extensively studied the neuroprotective effects of the Akt/mTOR pathways in stroke." (PMID 32832192, 2018). "In this study, we investigated the effect of CD4 T cell deficit on oxidative stress responses and the Akt/mTOR pathways in a mouse stroke model with transient MCA suture occlusion by using MHC II gene KO mice with dramatically reduced CD4 T cells." (PMID 32832192, 2018). "This study supports the continued research of mTOR modulation as a potential target for the development of novel treatments for ischemia/reperfusion injury in both in vitro and in vivo models of stroke." (PMID 23861877, 2013). "Together, these findings define an immunometabolic axis-AMPK/mTOR-arginine-TCA cycle coupling-that dictates microglial fate after stroke, and suggests VK as a therapeutic agent capable of concurrently targeting neuroinflammation, mitochondrial dysfunction, and metabolic imbalance." (PMID 42166856, 2026). "However, it has been shown that inhibition of mTOR by rapamycin in an adult model of stroke suppresses autophagy, prevents cytochrome c release, reduces ischemic brain damage 52, and improves motor impairments." (PMID 39744433, 2025). "The diminished expression of P62 and the elevated expression of LC3-II after inhibitor treatment compared to the OGD/R + Triolein group suggested that post-stroke autophagy inhibition by triolein was significantly attenuated following AKT/mTOR signaling pathway inhibition." (PMID 39639187, 2024).
Stroke (continued). "Catalpol activated the PI3K/Akt/mTOR pathway, decreasing the expression of miR-124 and increasing the expression of downstream protein S6, thus enhancing in vivo axon growth and neuronal survival in stroke models." (PMID 39202940, 2024). "Additionally, it promotes axon regeneration in both in vitro and in vivo stroke models via the PI3K/AKT/mTOR pathway." (PMID 38756705, 2024). "Since autophagy is repressed by the activation of this signaling pathway, we postulated that triolein could potentially activate the AKT/mTOR signaling pathway, thereby suppressing heightened post-stroke autophagy." (PMID 39639187, 2024). "In addition, activation of Akt/mTOR signaling pathway can promote the growth of posterior axons and improve the functional recovery after stroke." (PMID 36348200, 2023). "On the other hand, several studies confirmed that the activation of mTOR signaling in CNS neurons could prompt axonal regeneration by knocking out PTEN or manipulating other genes in spinal cord injury or stroke models." (PMID 38015348, 2023). "Recent studies have provided evidence that the neuroprotective effects of mTOR on stroke may be due to its ability to increase PSD95 and GAP-43 protein levels or promote neuronal structural stability in peri-infarct regions." (PMID 35211177, 2022). "Alternatively, hyperactivation of mTOR and increased GluR1 expression may represent a physiological reaction to the acute stroke insult." (PMID 35465399, 2022). "Evidence suggests that the links between the Akt and mTOR pathways may be important for reducing brain injury in the context of stroke." (PMID 35625605, 2022). "Of particular interest, it has been shown that melatonin post-stroke neuroprotective activity is partially dependent on mitophagy activation and that rapamycin, an Mechanistic Target Of Rapamycin Kinase (mTOR) inhibitor, activates mitophagy and alleviates vascular dementia." (PMID 33918863, 2021). "These may include where ischemia/apoptosis or stroke is the overriding pathology noting that mTOR has anti-apoptosis properties, or where oxidative stress is of higher concern such as in certain PD and ALS models." (PMID 34215308, 2021). "Interestingly, NPRL3 single nucleotide polymorphism has been associated with ischemic stroke susceptibility and post-stroke mortality, which can be related with increased mTOR activity, that is known to accelerate brain recovery after stroke." (PMID 34685669, 2021). "This study provides new mechanistic insights on how Hcy exerted neurotoxicity and enhances pathogenesis of stroke, implicating the PI3K-AKT- and ERK- dependent mTOR pathway as potential therapeutic targets for the stroke patient especially due to genetic disorders of Hcy metabolism." (PMID 31332165, 2019). "In addition, we and others have reported that stroke results in the activation of the Akt/mTOR neuronal survival signaling pathways." (PMID 32832192, 2018). "In our study, we did not observe a major involvement of TLR-4 and its downstream Traf6 signaling suggesting that CD8 could be a major upstream activator of mTOR/NF-κB in stroke." (PMID 29342151, 2018).
Stroke (continued). "Therefore, activated VEGF and BDNF-AKT/mTOR pathway played important roles in angiogenesis and neurogenesis post-stroke." (PMID 27465579, 2016). "To test whether our combination treatment of therapeutic agents and BMSC can influence ischemic cortical AKT/mTOR signaling pathway post-stroke, we applied western blot assay." (PMID 27465579, 2016). "In IS, mTOR activation is bifurcated: it supports cell survival via protein synthesis and metabolism, yet unchecked activity may drive dysfunction, contributing to stroke pathogenesis." (PMID 39846000, 2024). "Indeed, further experiments where mTOR is inhibited and or GluR1 is expressed in the recovery phase of stroke are needed to test this hypothesis." (PMID 35465399, 2022). "It is suggested that the activities of the mTOR pathway may be regulated by miRNA-199a-3p after stroke-related ischemic injury, but to the best of our knowledge, the molecular mechanism involving mTOR and miRNA-199a-3p has rarely been investigated in the hypoxic injury of neurons." (PMID 33110474, 2020). "Therefore, targeting the mTOR pathway in the CNS through IN delivery could be a way to reduce the detrimental effects not only due to Down syndrome and stroke, but also other neurological diseases that have increased mTOR activity." (PMID 33233734, 2020). "Additionally, increased mTOR activity has been shown to facilitate brain recovery after stroke." (PMID 33202874, 2020). "Furthermore, FTY720 could reverse the enhanced effects of mTOR inhibitor, rapamycin, on autophagy following stroke." (PMID 29186197, 2017). "Acupuncture was applied at GV14, GV26, GV20, and GV24, demonstrating an effect on post-stroke depression in rats, the mechanism of which is related to the activation of the PI3K/Akt/mTOR pathway; EA reduces post-stroke central pain." (PMID 40001566, 2025). "The neuro-functional recovery observed after stroke was enhanced by miR-17-92-cluster-enriched MSC exosomes, which may be linked to increased axonal extension and myelination, and mediated through the activation of the PTEN-mediated PI3K/Akt/mTOR pathway or via PI3K/AKT/VEGFA." (PMID 40565557, 2025). "Collectively, these findings indicate that triolein exerts inhibitory effects on post-stroke inflammation and autophagic responses through AKT/mTOR signaling pathway modulation." (PMID 39639187, 2024). "Lithium, an inhibitor of GSK-3β, activates mTOR through the Wnt/GSK-3β pathway, inhibits autophagy, and improves ischemic brain damage in the MCAO rat model of stroke." (PMID 38792655, 2024). "LBP activated AMPK/mTOR signaling pathway by increasing the enrichment and transfer of miR-133a-3p in NSC-EVs to inhibit stroke-induced autophagy activity." (PMID 37691119, 2023). "It is also important that CKLF1-induced glycolysis was dependent on the regulation of AMPK/mTOR signaling pathway, and both mTOR and AMPK were once considered as potential therapeutic targets for the treatment of stroke." (PMID 37098609, 2023). "Examples include: the synergy of anti-PD-1 and endostar on PI3K/AKT/mTOR-mediated autophagy; ginsenoside Rg1 promotes cerebral vascularization via the PI3K/AKT/mTOR pathway after stroke." (PMID 35712089, 2022). "Resveratrol considerably improved neurological function and inhibits the apoptosis of neuron cells after stroke, which is partially induced by activation of the JAK2/STAT3/PI3K/AKT/mTOR signaling pathway." (PMID 36278158, 2022). "To explore the potential molecular mechanisms of EGCG in stroke, we determined the effect of EGCG on AKT, p-AKT, AMPK, p-AMPK, mTOR, and p-mTOR in the ischemic hemisphere brain tissue by Western blotting assay." (PMID 36147330, 2022). "In summary, we determined that activation of the mTOR signaling pathway and increased expression of GAP-43 and SYN after stroke are beneficial to axonal regeneration and neurological recovery." (PMID 36440366, 2022).
Stroke (continued). "Moreover, LY294002 significantly down-regulated the expressions of PI3K/Akt/mTOR signaling pathway related factors, which demonstrated that I/R injury was relieved, and that PI3K/Akt/mTOR signaling pathway inhibition might be effective to treat stroke induced by I/R." (PMID 35095491, 2021). "VX‐765 protects HUMSCs against stroke‐induced apoptosis and inflammatory responses by activating autophagy via the AMPK/mTOR signaling pathway in vivo and in vitro." (PMID 32459063, 2020). "Phosphorylated Akt, PTEN, mTOR, P70S6K, and S60 protein levels are increased after stroke in the ischemic brain, suggesting a stimulating effect of stroke on these protective proteins." (PMID 32832192, 2018). "Apoptosis is reported to be responsible for a significant proportion of the HI-induced neuronal loss, and multiple apoptosis-related signal pathways, such as PI3K-Akt-mTOR/JNK, are involved in neuronal death after stroke." (PMID 29696512, 2018). "Meanwhile, it showed that SF and BP combined with BMSC treatment notably up-regulated AKT/mTOR signal pathway compared with SF + BP group and BMSC alone post-stroke." (PMID 27465579, 2016). "mTOR is also dysregulated in several neurological diseases, such as traumatic brain injury (TBI), stroke, and neurodegenerative disease." (PMID 24602288, 2014). "cPKCγ-modulated sequential reactivation of mTOR inhibited autophagic flux in neurons exposed to OGD/R, which may provide endogenous interventional strategies for stroke, especially ischemia/reperfusion injury." (PMID 29734780, 2018). "Western blot analysis revealed that stroke decreased the activity of PI3K/Akt/mTOR pathways compared with non-ischemic rats." (PMID 25954164, 2015). "Compared to sham, vehicle-treated stroke rats demonstrated decreased phosphorylation of mTOR in ROI-A and B (but not ROI-C), and MB-treated stroke rats displayed a further reduction in the phosphorylation of mTOR in ROI-A and B but not in ROI-C." (PMID 26121129, 2015). "Using expression profiling data and validating corresponding miRNAs to mRNA targets, we have proposed that Hedgehog, Notch, Wnt, mTOR and TGF-β pathways may be involved in bringing about the recovery process in the post ischemic phase of stroke." (PMID 23823624, 2013). "Stroke pathology prominently involves hyperactivation of major biological pathways, such as PI3K/AKT/mTOR, which disrupt cell adhesions, promote fibroblast migration and cell proliferation, all which may contribute to intimal vessel wall morphological changes and eventual vasoocclusion." (PMID 39790183, 2025). "Similarly, immunoblotting showed a marked increase in p-AMPKα, p-ULK1 (Ser 317), and active caspase-3 plus a greater reduction in p62/SQSTM1, p-mTOR, mTOR, p-S6, p-4E-BP, and p-ULK1 (Ser757) in the ipsilateral cerebral cortex of CrT–/y mice 24 hours after stroke." (PMID 34324436, 2021). "In this regard, the protective actions of rapamycin against CoCl2-simulated hypoxia may be different in that they do not stem from inhibiting an increase in mTOR expression as occurs during reperfusion in an in vivo stroke model." (PMID 30594149, 2018). "Third, although stroke did not significantly alter the phosphorylation of PRAS40 between the Akt and the mTOR pathways, CD4 T cell deficit results in significantly higher levels of P-PRAS40 at 24 h compared with WT mice." (PMID 32832192, 2018). "Blood mRNA profile analysis in MAS patients showed that interleukin‐1(IL‐1), interferon, relaxin, mammalian target of rapamycin (MTOR) signaling, sequestosome‐1(SQSTMI1), and cAMP response element binding protein‐1 (CREB1) were differentially expressed compared to stroke patients without malignancy." (PMID 38532275, 2024).